DHODH (dihydroorotate dehydrogenase (quinone))
Diseases named in the same sentence as DHODH in open-access papers (continued):
Sharing a sentence is not in itself a finding about the gene and the disease.
tumor (continued). "Recent studies have indicated that DHODH is involved not only in pyrimidine nucleotide biosynthesis but also in various other processes, such as cellular metabolism, growth signaling, ferroptosis, transcription, tumorigenesis, and tumor metastasis." (PMID 37744270, 2023). "Furthermore, combined with glutathione peroxidase 4 (GPX4)-knockdown, inhibition of DHODH by its inhibitor, brequinar, markedly suppressed xenograft tumor growth mediated by ferroptosis." (PMID 36788244, 2023). "Previous studies have found that either inhibiting CAD or DHODH, or direct targeting of pyrimidine metabolism, could inhibit tumor progression." (PMID 37240659, 2023). "This suggests that in addition to suppressing tumor growth by inhibiting pyrimidine biosynthesis, DHODH inhibitors could have a second mechanism of action that is, enhancement of ferroptosis." (PMID 37147673, 2023). "Dihydroorotate dehydrogenase (DHODH) is a powerful inhibitor of ferroptosis and has been demonstrated to inhibit cellular ferroptosis in tumor cells, but whether it can inhibit neuronal injury following spinal cord injury remains ambiguous." (PMID 36942513, 2023). "Since ferroptosis is activated in tumor cells, targeting DHODH to induce ferroptosis and inhibit tumor growth may provide a new target for cancer treatment." (PMID 37564215, 2023). "Here the authors report chemotherapy induces the phosphorylation of Lysyl oxidase-like 3, which in turn stabilizes dihydroorotate dehydrogenase (DHODH) and that DHODH inhibitor sensitizes tumor cells to oxaliplatin treatment by inducing ferroptosis in liver cancer." (PMID 37253718, 2023). "Previous studies have shown that DHODH, as a newly discovered third mechanism of ferroptosis, is accompanied by an increase in uridine content after the application of a ferroptosis activator in tumor cells." (PMID 37240659, 2023). "In this model, DHODH inhibition was also highly effective in preventing tumor growth." (PMID 35943801, 2022). "In tumor cells with low GPX4 expression, DHODH activity is significantly reduced or even inactivated, which gives rise to mitochondrial lipid peroxidation accumulation and activates ferroptosis, thereby inhibiting tumor growth." (PMID 35911967, 2022). "It was recently demonstrated that DHODH inhibition may suppress tumor growth in vivo by inducing ferroptosis." (PMID 35943801, 2022). "Thus, more diverse, and precise targeting strategies, such as proteolysis-targeting chimera (PROTAC) and molecular glue, are needed to negate the pro-tumor activity of DHODH." (PMID 34123854, 2021). "Taken together, this study suggests that polypharmacology may be currently exploited unknowingly, to achieve tumor cell elimination, and that more compounds, particularly those that are acidotropic with hydrophobic regions, may also interact with DHODH." (PMID 32900849, 2020). "The inhibition or downregulation of DHODH could help contain tumor cell proliferation, induce apoptosis, or enhance the antitumor effect of other target drugs." (PMID 32190695, 2020). "Importantly, we observed a synergistic effect of DHODH and Chk1 inhibition on tumor progression in vivo as well as its effect on metastases." (PMID 32034120, 2020). "Certain tenovins are also capable of blocking uridine uptake into cells, which may in fact potentiate the effect of DHODH inhibition when considering the effect on tumor cell viability." (PMID 32900849, 2020). "However, we found that CAD knockdown suppressed the in vivo tumor growth much more significantly than DHODH knockdown." (PMID 30643150, 2019). "Our data indicate significantly higher DHODH activity in HeLa cells (340 ± 25.9 pmol/105 cells/h) than in normal fibroblasts (54.1 ± 7.40 pmol/105 cells/h), and in malignant tumour tissue (1.10 ± 0.19 nmol/mg total proteins/h) than in adjacent normal tissue (0.24 ± 0.11 nmol/mg total proteins/h)." (PMID 28084471, 2017). "Early in 1959, the anti-proliferative effect of DHODH inhibitors was applied in tumor cells." (PMID 29348830, 2017).
tumor (continued). "Meanwhile, consistent with the results in vitro, the levels of DHODH protein and uridine in xenograft tumor were decreased significantly, verifying uridine plays a key role in apoptosis of xenograft tumor cells in vivo." (PMID 27374097, 2016). "Agents target certain mitochondrial processes, such as GPX4, DHODH, iron metabolism pathway, etc., to increase intracellular oxidative stress or attenuate the ferroptosis defense system, thereby inducing the ferroptosis of tumor cells and blocking tumor cell growth." (PMID 40083691, 2025). "In addition, studies in cell lines and animal models have shown that MEN1 mutations lead to an upregulation of the enzyme dihydroorotate dehydrogenase (DHODH), and administration of the DHODH inhibitor, leflunomide, attenuates cell growth and tumor progression." (PMID 38893191, 2024). "Our findings suggest that DHODH may be involved in the negative regulation of tumor cell apoptosis." (PMID 38796629, 2024). "DHODH shows significantly higher expression in CRC tumor tissue compared with normal samples using oncomine dataset analysis, which is consistent with a study that cell lines derived from the small and large intestine malignancies are most sensitive to DHODH knockdown." (PMID 33971967, 2021). "Finally, we assessed the potential anti-tumor effects of DHODH inhibition in a PDAC tumor model." (PMID 30470748, 2018). "Celastrol could also decrease uridine and DHODH protein level in tumor tissues." (PMID 27374097, 2016). "Recent preclinical studies have provided compelling evidence that pharmacological targeting of DHODH synergizes with GPX4 inhibitors, immune checkpoint blockade, or standard chemotherapeutics to enhance ferroptotic cell death and restrict tumor progression." (PMID 41369379, 2025). "To further assess combination DHODH and BCL-XL targeting as a therapeutic strategy for PDAC, we first evaluated for maximum tolerated doses of the combination of BQ and DT2216 in non-tumor bearing animal models." (PMID 40738904, 2025). "The inhibition of DHODH decreases ribosomal DNA transcription and leads to nucleolar stress in GBM cells and in GBM tumor xenografts." (PMID 38105543, 2025). "GSCs are also dependent on this biosynthetic pathway since targeting DHODH inhibits survival, self‐renewal and in vivo GBM tumor initiation." (PMID 38105543, 2025). "The combination of DHODH inhibition with Brequinar and BCL-XL degradation by DT2216, a proteolysis targeting chimera (PROTAC), significantly inhibits PDAC tumor growth." (PMID 40738904, 2025). "DHODH suppression attenuates TNBC tumor growth, mirroring the effects of PDE7A inhibition, and ectopic DHODH expression rescues PDE7A-inhibition-induced tumor suppression." (PMID 40961924, 2025). "DHODH inhibition induces a decrease in proliferation of GBM cells independently of the level of resistance to TMZ, and a reduction of tumor growth in vivo." (PMID 38105543, 2025). "Importantly, pharmacological inhibition of DHODH with agents such as brequinar or leflunomide resensitizes resistant cells to chemotherapy, suggesting that targeting DHODH could serve as a strategy to overcome resistance in multiple tumor types." (PMID 41369379, 2025). "Given the growing interest in targeting de novo pyrimidine synthesis as a PDAC dependency, we propose a combination strategy of DHODH and BCL-XL inhibition that can induce anti-tumor responses with potential clinical translatability." (PMID 40738904, 2025). "A deeper understanding of context-specific dependencies, such as the interplay between DHODH and GPX4 levels, the tumor lipidome, and immune microenvironmental cues, will be critical for rational clinical application." (PMID 41369379, 2025).
tumor (continued). "We found that PDE7A inhibitor, both alone and in combination with a DHODH inhibitor, suppressed TNBC tumor growth and metastasis." (PMID 40961924, 2025). "Recent studies have also shown that DHODH inhibition synergizes with ferroptosis inducers such as erastin or RSL3, amplifying lipid peroxidation and tumor cell death." (PMID 41369379, 2025). "To further examine the cell types expressing DHODH in tumor tissues, we used six datasets from the TISCH database to analyze the single-cell expression of DHODH." (PMID 38796629, 2024). "Herein, we report that DHODH inhibition induces the robust upregulation of APP genes and increases tumor cell antigen presentation via MHC-I." (PMID 37066260, 2024). "Targeting enzymes involved in pyrimidine synthesis, such as CAD protein (carbamoyl-phosphate synthetase 2, aspartate transcarbamylase, and dihydroorotase) and DHODH, inhibited GSC survival and self-renewal and reduced tumor growth in rodent models." (PMID 37298093, 2023). "Pharmacological inhibition of dihydroorotate dehydrogenase (DHODH), a crucial enzyme in this pathway, through the use of brequinar markedly reduced the viability of SCLC cells in vitro and suppressed tumor growth in vivo." (PMID 38203275, 2023). "DHODH and CAD expressions appeared greater in tumor tissues compared to adjacent tissues of HCC patients and were statistically significant." (PMID 37240659, 2023). "To further investigate the clinical relevance of AK2-mediated phosphorylation of LOXL3 and DHODH proteins in liver cancer, we first mined the TCGA-LIHC cohort and showed LOXL3 mRNA was upregulated in tumor tissues." (PMID 37253718, 2023). "Studies were performed in a MOLM-13 AML xenograft mouse models to correlate inhibition of DHODH with increases in DHO levels and reduction in tumor growth." (PMID 35223511, 2022). "Inhibition of DHODH by either shRNA or selective inhibitors impairs proliferation of OSCC cells and growth of tumor xenograft." (PMID 33510132, 2021). "Targeting the pyrimidine synthetic rate-limiting step enzyme CAD or the critical downstream enzyme DHODH markedly inhibits GSC survival, self-renewal, and in vivo tumor initiation through the depletion of the pyrimidine nucleotide supply in rodent models." (PMID 33971967, 2021). "Leflunomide treatment only modestly impacted primary tumor growth by two distinct CRC populations, suggesting enhanced sensitivity of CRC cells to leflunomide-mediated DHODH inhibition during liver metastatic colonization." (PMID 31841108, 2019). "Mechanistically, DHODH inhibition by H62 disrupted mitochondrial homeostasis, leading to increased ROS, caspase-3 activation, and cleavage of GSDME, which together initiated pyroptotic tumor cell death." (PMID 41239499, 2025). "This discovery has shifted DHODH from being regarded solely as a nucleotide metabolic enzyme to being recognized as a critical determinant of ferroptosis sensitivity, particularly in GPX4-low tumor contexts." (PMID 41369379, 2025). "DHODH-driven macropinocytosis sustains nutrient acquisition under conditions of scarcity and simultaneously represses MHC class II expression, thereby reducing tumor immunogenicity and contributing to immune escape." (PMID 41369379, 2025). "In addition, pharmacological inhibition of DHODH exerted a robust antiproliferative effect on NF2-deletion PM cells, as evidenced by reduced cell viability, colony formation, and tumor spheroid formation." (PMID 40707702, 2025). "Drug sensitivity and synergy in patient-derived organoids was consistent with our results in established PDAC cell culture models, suggesting that combination targeting of DHODH and BCL-XL may inhibit tumor growth in tumor models of PDAC." (PMID 40738904, 2025). "Similarly, we tested the combination of 5-fluorouracil (5-FU) and BRL-50481 based on the previous studies in which DHODH inhibitor and 5-FU have shown synergistic effects in tumor suppression and the fact that PDE7A inhibition can suppress DHODH expression." (PMID 40961924, 2025).
tumor (continued). "The mitochondrial enzyme DHODH similarly regenerates ubiquinol within the inner mitochondrial membrane, and dual inhibition of DHODH and GPX4 has been reported to induce profound ferroptosis in other tumor types." (PMID 41294853, 2025). "In the PPI network, DHODH was found to interact with UMPS and CAD to form enzyme complexes, facilitating pyrimidine biosynthesis in cells, thereby promoting DNA synthesis to regulate tumor cell proliferation and inhibit ferroptosis." (PMID 38796629, 2024). "Consequently, downregulating DHODH by OART disrupts redox balance in the mitochondria and makes tumor cells more vulnerable to ferroptosis." (PMID 38774917, 2024). "Next, to determine whether POLQ regulation of DHODH was crucial for POLQ‐induced tumor stemness, we performed spheroid formation assay using a stable GC cell line knockdown POLQ and overexpressing DHODH." (PMID 38575587, 2024). "In MEN1 mutation‐associated tumors, DHODH expression was enhanced due to the absence of MEN1 protein, leading to massive proliferation of tumor cells." (PMID 36925702, 2023). "Importantly, we demonstrated that UBE2T was positively correlated with p-Akt, β-catenin, CAD, DHODH, and UMPS in HCC tumor tissues." (PMID 35169125, 2022). "The ability of the combination therapy to inhibit tumor growth was significantly abrogated by uridine supplementation, indicating that the effects of BRQ in this therapeutic paradigm acted through inhibition of DHODH." (PMID 36453551, 2022). "In the non-tumor-bearing NHP, the DHO is from normal somatic tissue as all tissues express DHODH." (PMID 35223511, 2022). "Nevertheless, no palpable correlation was observed between DHODH expression and tumor locations, including tongue, gums, pharynx, jaw, or lower lip." (PMID 33510132, 2021). "Moreover, it is unraveled that inhibition of DHODH enables myeloid differentiation in human and mouse AML models via downregulating MYC which is a key transcription factor correlated with tumor cell differentiation." (PMID 33971967, 2021). "Importantly, treatment of tumor cells with the inhibitor of ferroptosis Fer-1, significantly reversed the increased sensitivity to CD8+ T cell-mediated killing in both BRQ treated and DHODH knocked-out (KO) cells." (PMID 41339932, 2025). "Moreover, the authors elegantly show that DHODH inhibitors elicit robust antitumor activity against NF2-altered mesothelioma and exhibit strong synergy with cisplatin, opening a new translational avenue for this tumor subtype." (PMID 40707701, 2025). "For example, inhibition of either DHODH or GPX4 alone did not induce ferroptosis in HT-1080 cells, which is likely due to the relatively high endogenous expression of GPX4 and DHODH; interestingly, a GPX4 inhibitor combined with a DHODH inhibitor could synergistically suppress HT-1080 tumor growth." (PMID 35814401, 2022). "Importantly, DHODH inhibitor brequinar selectively suppresses GPX4-low tumor growth by inducing ferroptosis, whereas combined treatment with brequinar and sulfasalazine synergistically induces ferroptosis and suppresses GPX4-high tumor growth." (PMID 35174081, 2022). "Moreover, mitochondrial localization of DHODH allows for targeting of leflunomide to mitochondria using a specific anchor, which could further increase the tumor sensitivity to this drug while minimizing its effects on normal cells." (PMID 32034120, 2020). "PDE7A-KO TNBC cells without or with DHODH overexpression were subcutaneously injected into the flanks of female NSG mice, and tumor growth was measured." (PMID 40961924, 2025).
tumor (continued). "By analyzing the effect of DHODH expression on the infiltration of 115 different subtypes of tumor immune cells using the TIMER 2.0 database, a negative correlation was noted between DHODH expression and most immune cell infiltrations." (PMID 38796629, 2024). "Note that in the absence of tumor formation at day 3, the expression of PPAT, IMPDH1, IMPDH2, DHODH but not PAICS are all statistically significantly elevated with MYC induction." (PMID 18628958, 2008). "Moreover, immunostaining of tumor tissue samples from syngeneic mice with and without LEF treatment showed a clear correlation with DHODH expression." (PMID 39815040, 2025). "To estimate the role of DHODH in regulating OSCC tumor growth, we established a mouse xenograft model by subcutaneous injection of HSC-3 cells that were stably expressed with non-target control (NC) shRNA or DHODH shRNAs." (PMID 33510132, 2021).
infection (8 papers, 2013 to 2024). The state of being infected such as from the introduction of a foreign agent such as serum, vaccine, antigenic substance or organism. "Thus, by targeting DHODH, the single key enzyme in viral genome replication and immune-regulation, a dual-action of DHODH can be realized in fighting against a broad spectrum of viruses and the corresponding pathogenic-inflammation in severe infections." (PMID 32754890, 2020). "To assess the antiviral activity in vivo of the novel DHODH inhibitors, we used the C57BL/6 mouse model of infection with the immunosuppressive CL-13 variant of the Armstrong strain of LCMV." (PMID 32751087, 2020). "By contrast, as compared to wild-type (WT) A549 cells, virus growth was largely inhibited in DHODH−/− cells with a 132-fold reduction of infectious particles at 72 h post-infection (h.p.i.)(black solid line vs. red solid line)." (PMID 32754890, 2020). "It is therefore difficult to resolve whether the enhanced lysis during infection was due to DHODH inhibition or cytotoxic effects of brequinar." (PMID 37869665, 2023). "However, DHODHi target the host DHODH, which keeps a relatively stable level during infection." (PMID 35632670, 2022). "By contrast, cell growth was not affected by lacking DHODH at all, indicating that de novo nucleotides biosynthesis is not indispensable in normal cell growth without infection at least for days." (PMID 32754890, 2020). "The Western blot results showed that the infection of Brucella M5 did not affect the expression of FSP1 and DHODH in RAW264.7 macrophages." (PMID 38790682, 2024).
hematologic malignancies (3 papers, 2022). "Previously, it has been reported that inhibition of DHODH in different hematological malignancies induces apoptosis and differentiation of the targeted cells." (PMID 35773274, 2022). "Of note, DHODH inhibition is currently under clinical investigation in patients with hematologic malignancies." (PMID 35943801, 2022). "DHODH inhibitors have demonstrated preclinical safety and are under clinical study for hematologic malignancies." (PMID 36453551, 2022).
infectious disease (2 papers, 2018 to 2019). A disorder directly resulting from the presence and activity of a microbial, viral, or parasitic agent in humans. "DHODH has been extensively explored as a potential drug target in rheumatology, oncology and infectious diseases studies." (PMID 30459406, 2018).
kidney diseases (1 paper, 2024). "This article reviews the development of the concept of ferroptosis, the mechanisms of ferroptosis (including GSH-GPX4, FSP1-CoQ1, DHODH-CoQ10, GCH1-BH4, and MBOAT1/2 pathways), and the latest research progress on its involvement in kidney diseases." (PMID 39021564, 2024).